LRP4 (LDL receptor related protein 4)
Diseases named in the same sentence as LRP4 in open-access papers (continued):
Sharing a sentence is not in itself a finding about the gene and the disease.
liver cancer (4 papers, 2018 to 2022). An epithelial or non-epithelial malignant neoplasm that arises from the liver. "Interestingly, agrin can serve as a mechanotransduction signal, which may transduce ECM and cellular rigidity signals to the Hippo pathway effector YAP, that requires both the Lrp4-MuSK signaling and integrin-focal adhesion signaling in liver cancer cells." (PMID 32208136, 2020).
osteoporosis (4 papers, 2020 to 2024). A condition of reduced bone mass, with decreased cortical thickness and a decrease in the number and size of the trabeculae of cancellous bone (but normal chemical composition), resulting in increased fracture incidence. "Several large GWAS have investigated the genetics of osteoporosis, revealing BMD-associated genes, including ESR1, LRP4, ITGA1, LRP5, SOST, SPP1, TNFRSF11A (RANK), TNFRSF11 (RANKL), and TNFRSF11B (OPG)." (PMID 39769358, 2024). "Numerous osteoporosis susceptibility loci, including ESR1, LRP4, DAAM2, WNT 16, and SOX 6, have been found and investigated using multiomics techniques based on systems genetics and genomics." (PMID 35496311, 2022).
amyloidosis (3 papers, 2021 to 2024). A disorder characterized by the localized or diffuse accumulation of amyloid protein in various anatomic sites. "Additional astrocyte hub genes in the ETC, including NRXN1, CADM1, MACF1, MAGI2, LRP4, GJA1 and ADGRL3, have been identified as markers of a reactive astrocyte state, implicating them in amyloidosis, regulation of neuroinflammation, cellular interactions." (PMID 38913039, 2024). "Furthermore, LRP4 is downregulated in the hippocampus, cortex, and entorhinal cortex of AD patients, and amyloid pathology is exacerbated in 5×FAD mice lacking LRP4, suggesting an important role for LRP4 in Aβ metabolism." (PMID 38280459, 2024).
glioma (3 papers, 2021 to 2023). A benign or malignant brain and spinal cord tumor that arises from glial cells (astrocytes, oligodendrocytes, ependymal cells). "MuSK-CAART cytotoxicity was subsequently evaluated against U87-MG glioma cells, which express MMP16 as well as LRP4." (PMID 36658341, 2023).
osteoarthritis (3 papers, 2023 to 2025). A noninflammatory degenerative joint disease occurring chiefly in older persons, characterized by degeneration of the articular cartilage, hypertrophy of bone at the margins and changes in the synovial membrane. "Oleandrin inhibits osteoclastogenesis via LRP4 in bone models, while digoxin exerts anti-inflammatory and chondroprotective effects through LRP4 in nucleus pulposus cells and osteoarthritis models." (PMID 40563525, 2025). "Antecedent reports have depicted LRP4 as a therapeutic target for digoxin in osteoarthritis treatment, while our research reveals a correlation between its dysregulation and IVDD." (PMID 37790932, 2023).
renal agenesis (3 papers, 2017 to 2023). Renal agenesis (RA) is a form of renal tract malformation characterized by the complete absence of development of one or both kidneys (unilateral RA or bilateral RA respectively), accompanied by absent ureter(s). "Lrp4 is also involved in the development of both the kidneys and limbs as Lrp4 knockout mice display abnormal limb morphology and renal agenesis." (PMID 28298885, 2017).
respiratory failure (3 papers, 2010 to 2018). The significant impairment of gas exchange within the lungs resulting in hypoxia, hypercarbia, or both, to the extent that organ tissue perfusion is severely compromised. "These Lrp4 null mutants had the expected digit defects, due to a loss of Lrp4 function, but in addition, the Lrp4 mutant mice died at birth due to respiratory failure." (PMID 29415504, 2018). "The agrin/Lrp4/MuSK signaling pathway is essential for survival as mice deficient for either agrin, Lrp4, MuSK or Dok-7 die at birth because of respiratory failure." (PMID 24520420, 2014). "Deletion of Lrp4 causes perinatal death due to an inability to form neuromuscular junctions and subsequent respiratory failure." (PMID 20383322, 2010). "While Lrp4 knockout mice fail to develop neuromuscular junctions and succumbed to respiratory failure post-natally, a truncated allele lacking the transmembrane and intracellular domains displays a mitigated phenotype compatible with postnatal survival." (PMID 20383322, 2010).
sarcopenia (3 papers, 2014 to 2024). Progressive decline in muscle mass due to aging which results in decreased functional capacity of muscles. "We also investigated effects of LMHFV in SAMP8 on the maintenance of NMJ during the onset of sarcopenia with respect to the Agrin‐LRP4‐MuSK‐Dok7 pathway and investigated the mechanism related to ERK1/2 signaling." (PMID 38532712, 2024). "Here we demonstrate that the agrin biologic NT-1654 is capable of activating the agrin/Lrp4/MuSK system in vivo, leading to an almost full reversal of the sarcopenia-like phenotype in neurotrypsin-overexpressing (SARCO) mice." (PMID 24520420, 2014).
syndactyly (3 papers, 2007 to 2021). A disease characterized by the presence of syndactyly, including syndromic and non-syndromic forms. "Recently, two independent mutations in the bovine LRP4 gene have been reported as the primary cause of syndactyly in the Holstein and Angus cattle breeds." (PMID 17319939, 2007). "The aim of this study was to screen the bovine LRP4 gene for co-segregating mutations in sixteen animals from different breeds affected by congenital syndactyly." (PMID 17319939, 2007). "Most interesting, four novel mutations in the bovine LRP4 gene were detected which possibly lead to syndactyly in cattle as none of these sequence variants was observed in chromosomes from unaffected control animals." (PMID 17319939, 2007). "However, the four newly described LRP4 mutations do still not explain all analyzed cases of syndactyly." (PMID 17319939, 2007).
van Buchem disease (3 papers, 2016 to 2024). "Cases were assessed clinically and underwent sequencing of known anabolic HBM loci: LRP5 (exons 2, 3, 4), LRP4 (exons 25, 26), SOST (exons 1, 2, and the van Buchem's disease [VBD] 52‐kb intronic deletion 3′)." (PMID 26348019, 2016).
autoimmune disorder (2 papers, 2022 to 2025). "Although direct studies on LRP4-MG pathophysiology are limited, the absence of thymic germinal center hyperplasia in most LRP4-MG patients suggests that peripheral lymphoid tissues may be the primary site of B cell–T cell interaction and autoimmunity." (PMID 41008338, 2025).
bipolar disorder (2 papers, 2023 to 2024). A disorder of the brain that causes unusual shifts in mood, energy, activity levels and the ability to carry out day-to-day tasks. "However, since PSI regulatory elements conveying evolution perspectives, they can bring new insights into complex regulation mechanisms as shown in the LRP4 example here and previous examples of SLC2A9 regulating urate levels and CACNA1C regulating Bipolar Disorder and Schizophrenia." (PMID 37056664, 2023).
diabetes (2 papers, 2020 to 2023). "Prior studies from the FORCE consortium have shown that LA is associated with lower risk of diabetes, thus it is possible that the association of LRP4 on diabetes risk factors is mediated by LA36." (PMID 37587153, 2023). "Expression of ASAH1, FES, and LRP4 was not affected by diabetes status." (PMID 32340285, 2020).
gastric cancer (2 papers, 2022). A primary or metastatic malignant neoplasm involving the stomach. "LRP4 overexpression has also been observed in gastric cancer tissues, where it correlates with malignant proliferating clinical features, while in gastric cancer cells (MKN45, MGC803, BGC823 and AGS), LRP4 activates the PI3K/AKT under regulation of miR-140-5p." (PMID 36012187, 2022). "LRP4 is overexpressed in papillary thyroid and gastric cancers, where it promotes EMT through PI3K/AKT pathwayand modulation of N-cadherin, ZEB1 and EZH2." (PMID 36012187, 2022). "Under the regulation of miR-140-5p, LRP4 accelerated cell migration and invasion in gastric cancer." (PMID 35293286, 2022).
motor neuron disease (2 papers, 2024 to 2025). "Antibodies against lipoprotein receptor–related protein 4 (LRP-4) may be found associated with the MuSK or AChR antibodies or in isolation, although they are also present in patients with motor neuron disease and patients without evidence of diseases." (PMID 39105625, 2024). "LRP4 antibodies occur in 2–5% of otherwise seronegative GMG patients but lack specificity, as they may also appear in motor neuron disease." (PMID 41255784, 2025).
pancreatic ductal adenocarcinoma (2 papers, 2025). An infiltrating adenocarcinoma that arises from the epithelial cells of the pancreas. "In line with our observation, pancreatic ductal adenocarcinoma CSC appears to release extracellular vesicles (EVs) loaded in agrin that will bind to non-CSC via LRP4 to promote YAP activation and subsequently non-CSC reprogramming into CSC." (PMID 40771583, 2025).
schizophrenia (2 papers, 2017 to 2023). A major psychotic disorder characterized by abnormalities in the perception or expression of reality. "Among these, the four genes most strongly altered in schizophrenia were WFS1 (P = 1.8×10−7), angiotensinogen (AGT, P = 1.3×10−6), LRP4 (P = 2.7×10−6), and TNS2 (P = 9.3×10−4), all of which were increased in schizophrenia." (PMID 29249829, 2017).
status epilepticus (2 papers, 2020 to 2024). Status epilepticus is defined as a continuous seizure lasting more than 30 min, or two or more seizures without full recovery of consciousness between any of them. "Most control mice (sh control lentivirus trans-infected mice) and sh Lrp4 scramble lentivirus trans-infected mice developed status epilepticus to score 5 (violent convulsions, falling over, death) after the fifth injection." (PMID 33292473, 2020). "In contrast, a majority of sh Lrp4 lentivirus trans-infected mice did not develop status epilepticus to score 5 even after the ninth injection." (PMID 33292473, 2020).
breast carcinoma (1 paper, 2025). "Altogether, these observations suggest that LRP4 expression is a clinically relevant biomarker for predicting breast cancer progression." (PMID 40771583, 2025). "We demonstrated that LRP4 knockdown reduced nuclear YAP in iCSC, resulting in an increase of breast cancer radio-sensitivity." (PMID 40771583, 2025). "Altogether, these results suggest that the LRP4/YAP axis is one of the key regulators of iCSC reprogramming and that LRP4 depletion may be a therapeutic opportunity to sensitize breast cancer cells to irradiation." (PMID 40771583, 2025).
breast tumors (1 paper, 2025). "We further demonstrate that overexpression of LRP4 is common in residual disease post-treatment and is associated with breast tumors of poor prognosis." (PMID 40771583, 2025). "Interestingly, we performed a gene set enrichment analysis (GSEA) on RNA-seq data from 1992 breast tumors (METABRIC) and observed that tumors with a high expression of LRP4 were positively associated with YAP/TAZ target genes in all individual subtypes including TNBCs." (PMID 40771583, 2025).
cardiomyopathy (1 paper, 2024). A disease of the heart muscle or myocardium proper. "Notably, our research has established a causal linkage between the APOL3 protein and cardiomyopathy, while the F11 and LRP4 proteins have been identified as potential culprits for ischemic stroke." (PMID 38820305, 2024). "APOL3, LRP4, and F11, on the other hand, have specific effects on cardiomyopathy and ischemic stroke, respectively." (PMID 38820305, 2024). "APOL3, LRP4, and F11, on the other hand, have specific effects on cardiomyopathy and ischemic stroke, respectively, all classified as highly recommended level protein targets." (PMID 38820305, 2024).
chondrosarcoma (1 paper, 2025). A malignant cartilaginous matrix-producing mesenchymal neoplasm arising from the bone and soft tissue. "A previous study that examined early and late OA tissues showed lower LRP4 expression in late OA cartilage tissues, and another that examined LRP receptors showed that they are modulated by mechanical stress in rat chondrosarcoma cell pellets." (PMID 39940775, 2025).
coronary artery disease (1 paper, 2021). "LRP6 and LRP4 were previously associated with AD and coronary artery disease." (PMID 33946285, 2021).
COVID-19 (1 paper, 2023). A disease caused by infection with severe acute respiratory syndrome coronavirus 2. "None of identified significant SNPs (in the intron of AJAP1 and the intron of FIG4) and none of the missense variants with a potential causal function on a severe outcome of COVID-19 (in the exon of PM20D1 and the exon of LRP4), found in our study, have been previously associated with COVID-19." (PMID 36662838, 2023). "The second missense variant was located in the exon of the low-density lipoprotein receptor-related protein 4 gene (LRP4) and two phenotypes, potentially related to COVID-19, were determined for it." (PMID 36662838, 2023). "We found no missense variants with a potential causal function on resistance to COVID-19; however, two missense variants were determined as significant a severe phenotype (in PM20D1 and LRP4 exons)." (PMID 36662838, 2023).
deafness (1 paper, 2022). An inherited or acquired condition characterized by the complete loss of the ability to hear from one or both ears. "Recessive homozygous c.4910G>A mutations of LRP4 have been recently discovered by clinical exome sequencing to be associated to unexplained KH in two siblings affected by Cenani-Lenz syndactyly, characterized by skeletal abnormalities, dysmorphisms, renal hypoplasia, deafness, congenital cataract." (PMID 35422763, 2022).
disc degeneration (1 paper, 2023). "To investigate whether the protective effect of digoxin against disc degeneration depended on LRP4 protein, we cultured primary human NP and transfected siRNA to knock down LRP4." (PMID 37790932, 2023).
glioblastoma (1 paper, 2017). The most malignant astrocytic tumor (WHO grade IV). "We examined the effects of LRP4 mRNA expression on patient survival in glioblastoma." (PMID 29088295, 2017).
Hypercholesterolemia (1 paper, 2007). An increased concentration of cholesterol in the blood.
Hypoglycemia (1 paper, 2022). A decreased concentration of glucose in the blood. "However, since LRP4 is a receptor involved in cell adhesion and receptor-ligand interactions in bone, kidney and nervous system, its putative role in the pathogenesis of hypoglycemia might be coincidental." (PMID 35422763, 2022).
Immunodeficiency (1 paper, 2016). Failure of the immune system to protect the body adequately from infection, due to the absence or insufficiency of some component process or substance. "Although our patients did not have prior symptoms suggestive of MG, it is possible that they had subclinical immunodeficiency and anti-LRP4 antibody may have caused additional symptoms after the onset of ALS in the context of the progression of axonal loss." (PMID 27863479, 2016).
migraine (1 paper, 2023). "Additionally, we note that many significant genes (e.g., AMBRA1, ATG13, ARHGAP1, CKAP5, LRP4, and DDB2) have been associated with migraine, headache, and proinsulin." (PMID 36808568, 2023).
muscle atrophy (1 paper, 2025). The loss of muscle tissue due to inactivity or disease. "The clinical data, imaging characteristics, treatment methods, and prognosis of one case of MG with AChR/LRP4 antibodies complicated by muscle atrophy were analyzed." (PMID 40356916, 2025). "Muscle atrophy in MG is rare, and it is even rarer in MG patients who are sera-positive for both AChR/LRP4 antibodies." (PMID 40356916, 2025). "This is a case report and literature review; the results and conclusions presented herein may not be generalizable for patients who were analyzed MG with AChR/LRP4 antibodies complicated by muscle atrophy." (PMID 40356916, 2025). "Literature on anti-AChR/LRP4 antibodies double-seropositive MG with muscle atrophy were reviewed." (PMID 40356916, 2025).
myocarditis (1 paper, 2023). Myocarditis is a condition that is characterized by inflammation of the heart muscle (myocardium). "Detected autoantibodies in patients with myositis, myocarditis or MG were anti-heart muscle (six cases), anti-skeletal muscle (six cases), anti-titin (five cases), anti-RyR (four cases), anti-AchR (three cases), and anti-LRP4 (one case) autoantibodies." (PMID 36845122, 2023).
osteosclerosis (1 paper, 2019). Abnormally high bone density. "A genome-wide association study (GWAS) has identified a correlation between LRP4 and bone density, while loss-of-function mutations (R1170W, W1186S) of LRP4 were found in a patient with osteosclerosis (OMIM: 614305)." (PMID 31698687, 2019).
papillary thyroid carcinoma (1 paper, 2025). "In contrast, LRP4 is upregulated in papillary thyroid carcinoma, where it promotes cell proliferation, migration and invasion." (PMID 40296873, 2025).
Polyhydramnios (1 paper, 2016). The presence of excess amniotic fluid in the uterus during pregnancy. "Therefore, we investigated the mechanisms underlying polyhydramnios observed in Lrp4−/− mice with bilateral kidney agenesis." (PMID 26847765, 2016). "Most Lrp4−/− foetuses showed unilateral or bilateral kidney agenesis, and Lrp4 knockout resulted in polyhydramnios." (PMID 26847765, 2016). "Close-to-term Lrp4−/− embryos (E17.5 and E18.5) showed polyhydramnios, and the weight of amniotic fluid in these mice was greater than in their wild-type and Lrp4+/− littermates." (PMID 26847765, 2016). "In order to investigate the relationship between the expression of AQPs and polyhydramnios in Lrp4−/− mice, we used RT-PCR to examine the expression of Lrp4 in the mouse placentas and foetal membranes of mice at E13.5, E17.5, and E18.5." (PMID 26847765, 2016). "Lrp4−/− foetuses showed polyhydramnios in the perinatal period." (PMID 26847765, 2016).
Respiratory insufficiency (1 paper, 2016). "Visual inspection suggested that newborn Lrp4−/− mice died due to respiratory insufficiency." (PMID 26847765, 2016).
Rett syndrome (1 paper, 2014). A severe neurodevelopmental disorder affecting the central nervous system. "Additionally, when suspended by the tail, Lrp4−/−; Lrp4m mice display a stereotyped limb clasping behavior, similar to other mouse models of neurological disorders, including Rett Syndrome." (PMID 25407677, 2014).
cancer (10 papers, 2010 to 2025). A tumor composed of atypical neoplastic, often pleomorphic cells that invade other tissues. "LRP4, a member of the low-density lipoprotein receptor family, has been implicated in various cancers." (PMID 40296873, 2025). "Further elucidation of the molecular functions of the LRP1b and LRP4 ECDs has the potential to provide novel and functionally significant insights into the role of LRP1b in embryogenesis and cancer." (PMID 20383322, 2010). "This contradictory expression pattern suggests that LRP4 may have context-dependent roles in different cancer types, potentially influenced by the tumor microenvironment." (PMID 40296873, 2025). "The results of previous studies have confirmed that SLC41A3, SEC61A1, LRP4, PPM1G, and HSP90AA1 play important roles in cancer progression." (PMID 35799605, 2022).